KL (klotho)
Diseases named in the same sentence as KL in open-access papers (continued):
Sharing a sentence is not in itself a finding about the gene and the disease.
cartilage disease (1 paper, 2019). Softening and degeneration of the CARTILAGE. "Wherefore, we believe that Klotho may be a potential target for the treatment of OA cartilage disease." (PMID 31895692, 2019).
cerebral atherosclerosis (1 paper, 2019). Atherosclerosis of the cerebral vasculature. "Cerebral atherosclerosis, presence of HWMHs and ALIs, total SVD score and fibroblast growth factor-23 were significantly different according to quartiles of the plasma Klotho concentration." (PMID 31398214, 2019).
chordoma (1 paper, 2013). Chordomas are rare malignant tumors arising from embryonic remnants of the notochord in axial skeleton. "By comparing methylation patterns of blood from healthy individuals and chordoma patients we found 20 significantly differentially methylated genes; 15 hypermethylated in chordoma (for example RASSF1, KL, RARB, HIC1, and FMR1) and 5 hypomethylated (HSD17B4, BAZIA, STAT1, NEUROGL, and JUP)." (PMID 23533570, 2013).
Crohn disease (1 paper, 2025). A gastrointestinal disorder characterized by chronic inflammation involving all layers of the intestinal wall, noncaseating granulomas affecting the intestinal wall and regional lymph nodes, and transmural fibrosis. "On the other hand, the correlations between circulating Klotho, LDL-C, and Crohn's disease susceptibility may not be affected by endocrine FGFs." (PMID 40119098, 2025).
cyst (1 paper, 2020). A sac-like closed membranous structure that may be empty or contain fluid or amorphous material. "Interestingly, serum klotho levels were reported to be inversely correlated with cyst volume according to one study." (PMID 32178226, 2020).
dermatitis (1 paper, 2024). An inflammatory process affecting the skin. "As opposed to Klotho knockout mice, they had no shortened lifespan, reaching over a year with no unusual health issues (only rare cases of dermatitis characteristic for the background at >6 months old were observed) and gained weight normally." (PMID 39277686, 2024).
diabetic eye disease (1 paper, 2020). A group of disorders affecting the eye in patients with diabetes mellitus. "Klotho may be a novel biomarker and potential treatment target for diabetic eye disease." (PMID 33225726, 2020).
diabetic foot ulcer (1 paper, 2021). "Studies have reported decreased serum Klotho concentrations and increased FGF-23 in patients with diabetic foot, and importantly, these parameters are independently associated with diabetic foot ulcers." (PMID 34721299, 2021).
diabetic maculopathy (1 paper, 2020). Diabetic maculopathy (DM) is a type of diabetic retinopathy and it is a major eye complication and visual impairment amongst people with diabetes. "Of the cohort of 81 patients, 22% (n = 18) had diabetic maculopathy at baseline and we did not observe any significant association between Klotho levels and progression of maculopathy." (PMID 33225726, 2020).
disc degeneration (1 paper, 2020). "We studied the expression of Klotho in the intervertebral disc and NP cells and elucidated the signal crosstalk between Klotho and the inflammatory signal, which is a potential trigger for disc degeneration." (PMID 32256598, 2020). "In addition, it is necessary to examine whether Klotho affects the activity of multiple signaling pathways in NP cells, including the activity of TGF, FGF, or MMP families that may be involved in disc degeneration." (PMID 32256598, 2020).
follicular thyroid cancer (1 paper, 2024). "Furthermore, klotho over-expression was shown to significantly reduce follicular thyroid cancer FTC133 and FTC238 cells proliferation and enhance apoptosis." (PMID 38696398, 2024).
fragile X-associated tremor/ataxia syndrome (1 paper, 2024). Fragile X-associated tremor/ataxia syndrome (FXTAS) is a rare neurodegenerative disorder characterized by adult-onset progressive intention tremor and gait ataxia. "In this study, the potential role and interaction of the APOε and KLOTHO genes on the penetrance of fragile X-associated tremor/ataxia syndrome (FXTAS) and on the IQ trajectory were investigated." (PMID 39125677, 2024).
geographic atrophy (1 paper, 2023). "In vivo experiments showed that intravitreally injected klotho inhibited the transition to migratory mesenchymal phenotypes in EMT and increased the cell size and irregularity, which can be observed in geographic atrophy or AMD." (PMID 37210384, 2023).
gout (1 paper, 2022). A condition characterized by painful swelling of the joints, which is caused by deposition of urate crystals. "Follow-up study should analyze data from the same time point to analyze the precise association between serum klotho levels and gout itself." (PMID 35351833, 2022).
Hyperoxaluria (1 paper, 2023). Increased excretion of oxalates in the urine. "In a model of renal injury caused by hyperoxaluria, vitamin C supplementation could restore the kidney Klotho protein level reduced by hydroxy-L-proline (HLP)-induced hyperoxaluria." (PMID 38231677, 2023). "In addition, the positive regulatory effect of vitamin C by inhibiting oxidative stress levels and thereby increasing Klotho levels has been demonstrated in rats with a hyperoxaluria model." (PMID 38231677, 2023).
hypertensive nephropathy (1 paper, 2024). Kidney damage that results from chronically elevated blood pressure; complications include glomerular damage resulting in proteinuria and hematuria. "Twelve patients with hypertensive nephropathy had a mean s.Klotho of 2.45 ng/mL and the median decrease in GFR was 7 mL." (PMID 39544340, 2024).
hypogonadotropic hypogonadism (1 paper, 2010). Abnormal ovarian or testicular function due to insufficient hormonal stimulation from the hypothalamic-pituitary axis. "Moreover, while a decrease in FGF8 signalling has been related to hypogonadotropic hypogonadism in human and mice, a similar syndrome was characterized in Klotho-deficient mice." (PMID 20844315, 2010).
Hypomagnesemia (1 paper, 2022). An abnormally decreased magnesium concentration in the blood. "First, mice with diet-induced hypomagnesemia have increased serum FGF23 levels and reduced renal Klotho expression, suggesting that dietary Mg2+ can influence the regulation of the FGF23-Klotho axis." (PMID 36699036, 2022).
hypoparathyroidism (1 paper, 2025). Hypoparathyroidism is an endocrine disorder in which the parathyroid glands in the neck do not produce enough parathyroid hormone (PTH). "This is linked to disturbances in bone-regulating factors, including relative hypoparathyroidism and changes in hormones, like FGF-23, sclerostin, and klotho, leading to bone disease." (PMID 39941397, 2025).
hypothyroidism (1 paper, 2024). Abnormally low levels of thyroid hormone. "In minimally adjusted model 1 (adjusted for age, sex, and race), each one-unit increase in serum Klotho was associated with a 54% reduction in the risk of hypothyroidism (OR = 0.46; 95% CI 0.29–0.74; P = 0.0014)." (PMID 38769411, 2024). "More studies are still needed to confirm further and elucidate the gender and age differences in the association between Klotho and hypothyroidism in older people." (PMID 38769411, 2024). "This study has the following limitations: firstly, due to the retrospective observational study design, it was impossible to determine the causal and temporal associations between serum Klotho levels and hypothyroidism in older adults." (PMID 38769411, 2024). "In the unadjusted model, each unit increase in serum Klotho was associated with a 47% reduction in the risk of hypothyroidism (OR = 0.53; 95% Cl 0.34–0.84; P = 0.0064)." (PMID 38769411, 2024). "With confounders adjusted, serum Klotho levels were negatively associated with hypothyroidism prevalence among older adults, and this was consistent across most subgroups." (PMID 38769411, 2024). "One plausible explanation for the association between serum Klotho levels and hypothyroidism in the elderly is aging." (PMID 38769411, 2024). "One of our study's main strengths is that it is the first to show an association between serum Klotho levels and hypothyroidism in older adults." (PMID 38769411, 2024). "We used a multivariate logistic regression model to investigate the association between serum Klotho (ln transformation) and hypothyroidism." (PMID 38769411, 2024). "In fully adjusted model 2 (adjusted for all covariates), each unit increase in serum Klotho was associated with a 51% reduction in the risk of hypothyroidism (OR = 0.49; 95% CI 0.31–0.80; P = 0.0039)." (PMID 38769411, 2024). "Serum Klotho (ln transformation) is independently and significantly negatively associated with the risk of hypothyroidism after complete adjustment for confounders (OR = 0.49, 95% CI 0.31–0.80; P = 0.0039)." (PMID 38769411, 2024). "It implies that higher serum Klotho levels may have a prominent role in reducing the risk of hypothyroidism in older adults." (PMID 38769411, 2024). "The relationship between serum Klotho levels and hypothyroidism in older people was analyzed by one-way analysis of variance, multiple linear regression models, subgroup analyses, interaction tests, smoothed curve fitting, and threshold effects." (PMID 38769411, 2024). "On the left side of the inflection point, serum Klotho (ln transformation) levels were positively correlated with hypothyroidism." (PMID 38769411, 2024). "Correspondingly, threshold effect analyses showed a significant inverted U-shaped relationship between serum Klotho (ln transformation) levels and hypothyroidism in the subgroups of 70 < age ≤ 75 years and females (P < 0.05 for log-likelihood ratio test)." (PMID 38769411, 2024). "The results of our study indicate that serum Klotho levels negatively correlate with hypothyroidism among older adults." (PMID 38769411, 2024). "Patients with hypothyroidism tend to be female and have lower glomerular filtration rate values as well as lower levels of serum Klotho concentrations than those with non-hypothyroidism." (PMID 38769411, 2024). "Klotho and hypothyroidism were negatively correlated in men, whereas there was an inverted U-shaped relationship in women." (PMID 38769411, 2024). "Our study concluded that serum Klotho levels negatively correlate with hypothyroidism in older adults." (PMID 38769411, 2024). "This study aimed to determine the relationship between serum Klotho levels and hypothyroidism in older adults." (PMID 38769411, 2024). "As far as we know, this is the first cross-sectional study to investigate the relationship between serum Klotho levels and hypothyroidism in a population-based, nationally representative sample of older adults." (PMID 38769411, 2024).
hypothyroidism (continued). "In addition, a linear relationship between Klotho (ln transformation) and hypothyroidism was revealed using smoothed curve fitting and threshold effect analysis." (PMID 38769411, 2024). "Age-stratified analyses showed an inverted U-shaped relationship between serum Klotho levels and hypothyroidism in the subgroup 70 < age ≤ 75 years, and we speculated that the limited number masked a linear correlation between the two." (PMID 38769411, 2024). "Additionally, there is a lack of research focusing on the association between Klotho and hypothyroidism in the elderly." (PMID 38769411, 2024). "Therefore, it is speculated that a decrease in Klotho levels is unfavorable for inhibiting aging, and serum Klotho levels are negatively correlated with the prevalence of hypothyroidism in elderly individuals." (PMID 38769411, 2024). "After ln transformation, Klotho showed a significant negative correlation with the prevalence of clinical hypothyroidism." (PMID 38769411, 2024). "Age, sex, race, serum Klotho level, and glomerular filtration rate were statistically significant in determining the presence or absence of hypothyroidism (P < 0.05)." (PMID 38769411, 2024). "Furthermore, despite our discovery of a negative correlation between serum Klotho levels in elderly individuals and hypothyroidism, it is important to note that hypothyroidism can be classified according to different criteria." (PMID 38769411, 2024).
idiopathic scoliosis (1 paper, 2023). A scoliosis with no known cause. "Currently, there are limited reports in the literature on Klotho protein and FGF-23 levels in adolescent idiopathic scoliosis." (PMID 37686090, 2023).
intrahepatic cholangiocarcinoma (1 paper, 2021). A carcinoma that arises from the intrahepatic bile duct epithelium in any site of the intrahepatic biliary tree. "Our study aimed to explore the functions of SNHG12 on intrahepatic cholangiocarcinoma (ICC) progression and its interaction with miR-199a-5p and Klotho." (PMID 34239888, 2021).
invasive ductal carcinomas (1 paper, 2020). "They noted higher Klotho protein expression in all normal breast samples and in 19% of normal breast samples adjacent to invasive ductal carcinomas or DCIS, compared with only 17% in DCIS and 22% invasive ductal carcinoma (p < 0.0001)." (PMID 32585905, 2020).
ischemia reperfusion injury (1 paper, 2020). Adverse functional, metabolic, or structural changes in ischemic tissues resulting from the restoration of blood flow to the tissue (reperfusion), including swelling; hemorrhage; necrosis; and damage from free radicals. "Furthermore, renal Klotho decreased in mice ischemia reperfusion injury (IRI), while overexpression Klotho played a renoprotective role in mice with ischemia-reperfusion injury (IRI)." (PMID 32571212, 2020).
kidney degeneration (1 paper, 2020). "Klotho may be a promising agent to attenuate senescence and ameliorate age-associated, and Pi-induced kidney degeneration such as kidney fibrosis." (PMID 32973510, 2020).
Left ventricular diastolic dysfunction (1 paper, 2018). Abnormal function of the left ventricule during left ventricular relaxation and filling. "Similar findings on the association between soluble Klotho and left ventricular diastolic dysfunction in adults has recently been reported." (PMID 28795324, 2018).
leukemia (1 paper, 2020). A malignant (clonal) hematologic disorder, involving hematopoietic stem cells and characterized by the presence of primitive or atypical myeloid or lymphoid cells in the bone marrow and the blood. "Consistent with accelerated myeloid lineage output from transplanted KLG FL cells, KLG mice developed leukemia more rapidly (average latency of 8 months) than KL mice (average latency of 10 months)." (PMID 32330454, 2020).
male infertility (1 paper, 2023). The inability of the male to effect fertilization of an ovum after a specified period of unprotected intercourse. "To characterize the functional pathways and molecules that contribute to the potential etiology of male infertility caused by diminished Klotho expression, we compared the testicular proteome between the 2-month-old control and Klotho-deficient groups including three individuals in each group." (PMID 37759974, 2023). "Understanding the effects of Klotho on male reproduction is beneficial for the clinical management and treatment of male infertility." (PMID 37759974, 2023). "However, further studies are necessary to fully understand the effects of Klotho on male infertility." (PMID 37759974, 2023).
membranous nephropathy (1 paper, 2022). "However, Klotho expression was inhibited and Smad3 signaling was activated in human kidney biopsies from CKD patients with membranous nephropathy (MN)." (PMID 35064106, 2022).
mesenchymal tumors (1 paper, 2019). "When limited organs such as renal tubular cells express Klotho under physiological conditions, we hypothesize that the ectopic expression of Klotho in these mesenchymal tumors may be involved in the pathogenesis of TIO." (PMID 30627598, 2019). "•Klotho is ectopically expressed in the FGF23-producing mesenchymal tumors." (PMID 30627598, 2019). "Therefore, we conclude that DNA methylation does not principally regulate Klotho expression in FGF23-producing mesenchymal tumors." (PMID 30627598, 2019).
monoclonal gammopathy of undetermined significance (1 paper, 2015). "Bone marrow plasma cells from 42 MM patients stained positively for klotho, while plasma cells from 8 patients with monoclonal gammopathy of undetermined significance (MGUS) and 6 controls were negative." (PMID 25944690, 2015).
multiple system atrophy (1 paper, 2019). Multiple system atrophy (MSA) is a neurodegenerative disorder characterized by autonomic failure (cardiovascular and/or urinary), parkinsonism, cerebellar impairment and corticospinal signs with a median survival of 6-9 years. "In addition, the level of serum Klotho has been also utilized to predict the onset of multiple system atrophy." (PMID 31001090, 2019).
nephritis (1 paper, 2023). Inflammation of renal tissue. "Whether Klotho inhibits nephritis by blocking IFNγ-targeted proteins and IFNγ downstream signaling remains unclear." (PMID 37213666, 2023).